CRMP1 (collapsin response mediator protein 1)
Description:
Necessary for signaling by class 3 semaphorins and subsequent remodeling of the cytoskeleton. Plays a role in axon guidance. During the axon guidance process, acts downstream of SEMA3A to promote FLNA dissociation from F-actin which results in the rearrangement of the actin cytoskeleton and the collapse of the growth cone. Involved in invasive growth and cell migration. May participate in cytokinesis.
Synonyms: DRP-1; CRMP-1; ULIP-3; DPYSL1; DRP1
Tractability: PROTAC: ubiquitination databases record sites on it; its protein half-life has been measured.
Gene: Protein-coding gene on chromosome 4 (5,748,084 to 5,893,086, reverse strand). Ensembl gene ENSG00000072832.
Subcellular location: Cytoplasm; Cytoplasm, cytoskeleton, microtubule organizing center, centrosome; Cytoplasm, cytoskeleton, spindle; Cell projection, growth cone; Cytoplasm, cytoskeleton; Perikaryon
Subcellular location (Human Protein Atlas): Centrosome; Cytosol
Pathways (Reactome):
Developmental Biology: CRMPs in Sema3A signaling
Gene Ontology:
Molecular function: filamin binding; identical protein binding; protein binding; dihydropyrimidinase activity; hydrolase activity; hydrolase activity, acting on carbon-nitrogen (but not peptide) bonds; phosphoprotein binding
Biological process: negative regulation of neuron projection development; nervous system development; nucleobase-containing compound metabolic process; pyrimidine nucleobase catabolic process; regulation of postsynapse assembly; semaphorin-plexin signaling pathway
Cellular component: centrosome; cytoplasm; cytosol; midbody; perikaryon; actin cytoskeleton; cytoskeleton; dendrite; growth cone; neuronal cell body; postsynapse; presynapse; spindle
Genetic constraint (gnomAD): Loss-of-function variants: 19 observed, 63.41 expected, observed/expected ratio (o/e) 0.3, 90% interval 0.21 to 0.44. The synonymous counts are far from expectation, so gnomAD's model fits this gene poorly and the ratio says little. Missense variants: 790 observed, 881.18 expected, observed/expected ratio (o/e) 0.9, 90% interval 0.85 to 0.95. Synonymous variants: 439 observed, 362.37 expected, observed/expected ratio (o/e) 1.21, 90% interval 1.12 to 1.31.
Homologues: Orthologues: chimpanzee CRMP1 (99% identical), guinea pig CRMP1 (98% identical), rat Crmp1 (97% identical), macaque CRMP1 (95% identical), dog CRMP1 (86% identical), pig CRMP1 (85% identical), tropical clawed frog crmp1 (84% identical), mouse Crmp1 (79% identical), zebrafish crmp1 (66% identical). Paralogues in human: DPYSL3 (68% identical), DPYSL2 (67% identical), DPYSL4 (57% identical), DPYS (44% identical), DPYSL5 (42% identical).
Diseases named in the same sentence as CRMP1 in open-access papers:
CRMP1 is named in the same sentence as 58 diseases in open-access papers, as found by Europe PMC text mining. Sharing a sentence is not in itself a finding about the gene and the disease. The quoted sentences say what the papers report.
schizophrenia (13 papers, 2013 to 2025). A major psychotic disorder characterized by abnormalities in the perception or expression of reality. "Knockout of Crmp1 in mice results in schizophrenia-associated behavior, impaired learning and memory, and prepulse inhibition." (PMID 36511780, 2022). "In humans, maternal CRMP1 autoantibodies have been associated with autism in their children, and increased CRMP1 mRNA levels were identified in individuals with schizophrenia, attention-deficit hyperactivity disorder, and ASD." (PMID 36511780, 2022). "In conclusion, our results suggest that CRMP1 is associated with some of the symptoms of schizophrenia and/or some related disorders." (PMID 24409129, 2013). "Thus, this suggests that CRMP1 is a malformed protein that could become a diagnostic marker for schizophrenia." (PMID 36430976, 2022). "Altered CRMP1 immunoreactivity manifested itself as an increase in CRMP1 in lymphoblastoid cell lines derived from patients with schizophrenia." (PMID 36430976, 2022). "It has been suggested that CRMP1 is involved in the pathogenesis of neurological diseases such as Huntington's disease and schizophrenia." (PMID 36237616, 2022). "CRMP1/2 expression and phosphorylation has been proposed as a biomarker for several neuropsychiatric pathologies including Alzheimer disease, schizophrenia, and epilepsy." (PMID 33483694, 2021). "CRMP1−/− mice showed impaired memory and behavioral abnormalities related to schizophrenia such as hyperactivity, altered emotional behavior and decreased prepulse inhibition." (PMID 31379804, 2019). "So far, established risk factors DISC1 and dysbindin were seen to specifically aggregate in a subset of such patients, as was a novel schizophrenia-related protein, CRMP1, identified through a condition-specific epitope discovery approach." (PMID 25333879, 2014). "Intriguingly, both mouse models show schizophrenia-like behavior, indicating the commonly shared cellular mechanism for dendritic development In the hippocampal slices of both Crmp1+/− and Crmp1−/− mice, LTP induction was impaired." (PMID 36511780, 2022). "Interestingly, a related protein, CRMP1, was detected as aggregates, exclusively in the postmortem brain samples from schizophrenia." (PMID 31591136, 2019). "Interestingly, lymphoblastoid cell lines derived from schizophrenia patients show an abnormal level of CRMP1 expression, suggesting its potential role as a blood-based diagnostic marker." (PMID 24409129, 2013). "Taken together, these findings raise the possibility that CRMP1 may be involved in the pathophysiology in schizophrenia." (PMID 24409129, 2013). "Thus, CRMP1 could be a novel candidate protein for the investigation of schizophrenia mechanisms, which functionally interact with DISC-1 and intersect with the reelin and DISC-1 pathways." (PMID 36430976, 2022). "Proteins such as DISC1, CRMP1, NOS1AP, and others have been identified with altered expression and aggregation patterns in schizophrenia, linking protein abnormalities to disease pathology." (PMID 41217487, 2025). "In addition, findings obtained from Crmp1- and Crmp2-KO mice suggest that impairments in CRMP1 and CRMP2 functions are involved in the pathogenesis of schizophrenia." (PMID 31137494, 2019). "Of particular note, TARA and CRMP1, another substrate of GSK3, have been identified in insoluble aggregates present in brain samples of schizophrenia patients, hinting at the potential involvement of TARA-DYRK2-GSK3β signaling module in the associated disease pathogenesis." (PMID 31815665, 2019).
lung carcinoma (10 papers, 2011 to 2024). "The fifth protein is human collapsin response mediator protein-1 (CRMP-1), which is associated with axonal guidance and neuronal development, and in lung cancer, it has been identified as a potential tumour suppressor." (PMID 38203761, 2024). "CRMP1 is a tumor suppressor, and low expression of CRMP1 mRNA in lung cancer tissue was significantly associated with disease progression, LNM, early postoperative recurrence, and shorter survival." (PMID 36454866, 2022). "A previous study evaluated the association between CRMP1 expression in tumors and clinical outcome in 80 lung cancer patients." (PMID 24765134, 2014). "The functional difference between CRMP1 and LCRMP1 has previously been investigated in non-small-cell lung cancer (NSCLC) Low CRMP1 mRNA expression in lung cancer tissue was significantly associated with advanced disease, lymph node metastasis, early post-operative relapse, and shorter survival." (PMID 27475326, 2016). "This study implicated CRMP1 as a novel invasion suppressor gene in lung cancer." (PMID 24765134, 2014). "CRMP-1 encodes an intracellular phosphoprotein and was found to be suppressed or lost in several human cancers, especially primary malignant brain tumors and lung cancers." (PMID 24213137, 2011). "In vitro study demonstrated that invasive activity was dramatically reduced in CRMP1 expressing lung cancer cells." (PMID 26009886, 2015). "Cyclooxygenase-2 (COX-2) is considered to be important in the regulation of CRMP1 in lung cancer; the overexpression of COX-2 has been reported to decrease CRMP1 mRNA and protein expression." (PMID 24765134, 2014). "CRMP1 was described to act as a tumor suppressor gene in lung cancer." (PMID 34680167, 2021). "Although reduced CRMP1 expression was associated with clinical outcomes in lung cancer, we did not detect a link between CRMP1 and progression-free survival (PFS) or overall survival (OS) in either our panel of samples or the two expression dataset cohorts." (PMID 26009886, 2015). "Aberrant expression of CRMP1 has been reported in lung cancer." (PMID 26009886, 2015). "In lung cancer, CRMP1 expression is significantly downregulated compared to adjacent normal tissue." (PMID 26009886, 2015). "Transfection of a CRMP1 construct into a highly invasive lung cancer cell line was found to significantly reduce the invasive activity of the cells, whereby morphological changes (from an elongated to a rounded morphology) and a reduction in filopodia were observed." (PMID 24765134, 2014). "Therefore, COX-2 may increase metastasis by the regulation of CRMP1 expression in lung cancer cells." (PMID 24765134, 2014). "Thus, CRMP1 may function as a novel invasion suppressor gene in lung cancer." (PMID 27475326, 2016). "The present study summarized that different members of the CRMP family are involved in different tumors; CRMP1 and CRMP2 in lung cancer, CRMP2 in breast and colorectal cancer, CRMP4 in prostate cancer, pancreatic cancer and neuroblastoma, and CRMP5 in neuroendocrine lung cancer and glioblastoma." (PMID 24765134, 2014). "In lung adenocarcinoma Cl1-5 cells, which have high metastatic potential, CRMP-1 expression was demonstrated to be greatly suppressed and overexpression of CRMP-1 inhibited their metastatic ability, confirming the critical role of CRMP-1 in the invasion of lung cancer." (PMID 24213137, 2011). "Although many molecules, such as caveolin-1, CRMP-1 and CTGF, have been reported as being important in promoting or inhibiting invasion and metastasis of lung cancer based on the cell line series, this model has not been used in radiation-related studies to date." (PMID 23614048, 2013).
autism (7 papers, 2019 to 2025). Persistent deficits in social interaction and communication and interaction as well as a markedly restricted repertoire of activity and interest as well as repetitive patterns of behavior. "The CRMP1 (p.K586Rfs*75) frameshift variant was identified in this patient, with the following phenotypes: autism/autism spectrum disorder, stereotypic behavior, social impairment, delayed speech and language development, poor eye contact, and attention deficit hyperactivity disorder." (PMID 39758889, 2024). "Additionally, we found that maternal autoantibody reactivity to CRMP1 significantly increases the odds of a child having a higher Autism Diagnostic Observation Schedule (ADOS) severity score (OR 2.3; 95% CI: 1.358–3.987, p = 0.0021)." (PMID 33483694, 2021). "In our clinical studies, CRMP1+CRMP2 has been the most prevalent MARA autoantibody pattern and is most highly associated with a more severe autism phenotype." (PMID 39929953, 2025). "Early clinical studies identified that mothers with the combination of LDHA/B+STIP1+CRMP1 autoantibodies had children with a more severe autism phenotype compared to mothers of children with autism who lacked autoantibodies." (PMID 39929953, 2025). "The authors used the immuno-dominant B-cell epitopes of LDH-A, LDH-B, STIP1 and CRMP1 to produce an antigen-driven model based on the autism-specific 37/73 kDa band pattern." (PMID 32784803, 2020). "Furthermore, the CRMP1+CRMP2 MARA pattern has been found to correlate with more severe developmental delay in addition to autism in affected children." (PMID 39929953, 2025). "We found that exposure to maternal CRMP1+CRMP2 autoantibodies elicits the strongest DE response with over 1390 DE genes passing FDR < 0.1, which aligns with our clinical observation that CRMP1+CRMP2 is associated with a more severe autism phenotype." (PMID 39929953, 2025). "We present a case of a boy with a heterozygous de novo variant in the CRMP1 gene, identified through whole-exome sequencing (WES), who exhibits phenotypes of a neurodevelopmental disorder such as autism, language delay, hyperactivity, and learning disabilities." (PMID 39758889, 2024). "It has been shown that autoantibodies targeting the intracellular proteins LDH-A and LDH-B, STIP1 and CRMP1 are able to induce autism-related behavioral changes in a mouse model, however, but how these antibodies target their antigens is also still unknown." (PMID 36816132, 2023). "In contrast, the CRMP1+GDA pattern is less commonly associated with increased odds of intellectual disability (ID) and is significantly higher in the autism with no ID population." (PMID 39929953, 2025).
neuroblastoma (4 papers, 2014 to 2022). Neuroblastoma (NB) is the most common solid, extracranial childhood tumor. "The two peptides assigned to CRMP1 had significantly lower intensities in tumor cell-rich areas from high-risk neuroblastomas compared to lower risk classifications." (PMID 34202325, 2021). "Our data showed a lower intensity distribution of CRMP1 in high-risk neuroblastomas and reciprocally higher intensity distribution in low- and intermediate-risk neuroblastomas." (PMID 34202325, 2021). "In contrast, CRMP1 staining is intense in tumor cell-rich regions of neuroblastomas with other risk designations and only exhibited slight staining in the high-risk group." (PMID 34202325, 2021). "Reciprocally, CRMP1 expression was lower in high-risk neuroblastomas compared with lower risk groups, validating our MALDI-MSI profiling results." (PMID 34202325, 2021). "Likewise, the relatively low intensity 922.50 m/z peak in MALDI-MSI of high-risk neuroblastomas is a tryptic peptide from CRMP1, a marker for neuronal differentiation that is involved in neuronal outgrowth and guidance." (PMID 34202325, 2021). "The AHNAK nucleoprotein and collapsin response mediator protein 1 (CRMP1) were identified as proteins associated with these peptide signatures, and their differential expression in the neuroblastomas of divergent risk was immunohistochemically validated." (PMID 34202325, 2021). "A detailed functional assessment of the biological role of CRMP1 in neuroblastoma is warranted in subsequent studies, but is beyond the scope of this paper." (PMID 34202325, 2021). "To clarify the potential role of Thr509 phosphorylation in neuron CRMP1, we examined how the overexpression of the phospho-mimicking CRMP1 mutant Thr509Asp-CRMP1 affected neurite outgrowth in murine neuroblastoma Neuro2a cells, which are commonly used to study neuronal cytoskeletal dynamics." (PMID 36237616, 2022). "Differential expression of the identified discriminative proteins, AHNAK and CRMP1, was immunohistochemically confirmed in sections, and discriminative spatial intensities of m/z peaks were validated in microarrayed tissue cores from tumor cell-rich regions in neuroblastomas." (PMID 34202325, 2021).
amyotrophic lateral sclerosis (3 papers, 2022 to 2023). Amyotrophic lateral sclerosis (ALS) is a neurodegenerative disease characterized by progressive muscular paralysis reflecting degeneration of motor neurons in the primary motor cortex, corticospinal tracts, brainstem and spinal cord. "Phosphoproteomic analysis showed that the semaphorin neuronal repulsive signaling pathway, which includes Crmp1 phosphorylation at Ser522, is upregulated in SOD1G93A mice that serve as a model of amyotrophic lateral sclerosis (ALS)." (PMID 35523582, 2022).
autism spectrum disorder (3 papers, 2022 to 2025). A spectrum of developmental disorders that includes autism, and Asperger syndrome. "For example, monoallelic variants in the CRMP1 gene cause a neurodevelopmental disorder characterized by muscular hypotonia, intellectual disability, and/or autism spectrum disorder." (PMID 40583162, 2025). "Here, we link for the first-time CRMP1 variants in three unrelated pedigrees to neurodevelopmental disorder in humans with muscular hypotonia, autism spectrum disorder (ASD), and/or intellectual disability." (PMID 36511780, 2022). "We report heterozygous de novo variants in the CRMP1 gene in three unrelated individuals with muscular hypotonia, intellectual disability, and/or autism spectrum disorder." (PMID 36511780, 2022). "Peptide microarray experiments have shown that the antigenic epitope of CRMP1 can be recognized and bound by plasma samples from the mothers of children with autism spectrum disorders." (PMID 40583162, 2025).